RUNX3 (RUNX family transcription factor 3)
Diseases named in the same sentence as RUNX3 in open-access papers (continued):
Sharing a sentence is not in itself a finding about the gene and the disease.
gastric cancer (continued). "In all, 35/55 (63.6%) of the clinical gastric cancer specimens showed reduced expression of RUNX3 as compared with surrounding normal mucosa." (PMID 24447545, 2014). "We examined the effect of increased or decreased RUNX3 expression on the invasion potential of human gastric cancer cells and the expression of the EMT molecules vimentin and E-cadherin." (PMID 24447545, 2014). "Overexpression of RUNX3 suppressed cell invasion and decreased the protein expression of vimentin in the cells and inhibited gastric cancer cells colonization in nude mice." (PMID 24447545, 2014). "Knockdown of RUNX3 promoted cell invasion and increased the protein expression of the mesenchymal marker vimentin in human gastric cancer cells." (PMID 24447545, 2014). "In this study, RUNX3 inhibition and overexpression increased and decreased human gastric cancer cell invasion respectively." (PMID 24447545, 2014). "Statistical analysis showed that RUNX3 and miR-30a levels were highly correlated in gastric cancer samples (P < 0.0001)." (PMID 24447545, 2014). "RUNX3 was first reported to correlate with the genesis and progression of human gastric cancer as a tumor suppressor." (PMID 24475196, 2014). "Our data provide a novel mechanism for RUNX3-mediated suppression of gastric cancer invasion and metastasis." (PMID 24447545, 2014). "Runx3 is an important tumor suppressor that is inactivated in gastric cancer, and promoter hypermethylation of Runx3 is frequent." (PMID 23629677, 2013). "Peng demonstrated that RUNX3 down-regulated VEGF expression via transcriptional repression in human gastric cancer." (PMID 23457532, 2013). "It was found that dramatic loss of Runx3 protein was associated with VEGF overexpression and increased microvessel density in human gastric cancer." (PMID 23874686, 2013). "Runt-related transcription factor 3 (RUNX3), located in chromosome 1p36, was first reported as a tumor suppressor gene for gastric cancer." (PMID 23426905, 2013). "RUNX3 is inactivated in gastric cancer by hemizygous deletion, promoter hypermethylation, histone modification, and protein mislocalization, suggesting a tumor-suppressive role of RUNX3 in this malignancy." (PMID 23637848, 2013). "Restoration of Runx3 expression significantly inhibited gastric cancer cell growth in vitro and tumorigenicity and metastasis in animal models and correlated with transcriptional repression of VEGF expression." (PMID 23874686, 2013). "Analysis of clinical tissue samples from peritoneal metastases arising from gastric cancers showed that RUNX3 expression decreased significantly in the metastatic tissue, compared to normal gastric mucosa or primary main tumors." (PMID 23457532, 2013). "Since the discovery of the potential role of RUNX3 in the initiation and the progression of gastric cancer, RUNX3 has been found to be involved in the development of a variety of cancers, including colon, liver, lung and breast cancer." (PMID 23637848, 2013). "The decreased expression of Hlx, T-bet, and Runx3 were found in each histological type of gastric cancer." (PMID 23243425, 2012). "The expression levels of Hlx, T-bet, IFN-γ, and Runx3 mRNA from 90 patients with gastric cancer and 46 healthy controls were measured by QRT-PCR." (PMID 23243425, 2012). "In order to understand the relationship between the Runx3 and T-bet expressions in gastric carcinoma sufferers, we analyzed the Runx3 mRNA levels in PBMCs of patients." (PMID 23243425, 2012). "For one example, Runx3 has been shown to suppress gastric cancer metastasis through the inactivation of MMP-9 by the upregulation of TIMP-1." (PMID 21904555, 2011). "The ORs for RUNX3 methylation in well-differentiated vs undifferentiated gastric cancers, and in intestinal-type vs diffuse-type carcinomas were 0.59 (95%CI: 0.30, 1.16) and 2.62 (95%CI: 1.33, 5.14), respectively." (PMID 21867527, 2011).
gastric cancer (continued). "Previous studies have also reported increased methylation of RUNX3 in stage I and II gastric cancers, suggesting that the RUNX3 gene contributes to gastric cancer development." (PMID 21867527, 2011). "The remaining 17 studies included data on the relationship between RUNX3 gene promoter methylation and gastric cancer, and these studies were pooled for analysis." (PMID 21867527, 2011). "In gastric cancer, a hypoxia-induced epigenetic silencing of the tumour suppressor RUNX3 through histone H3-lysine 9 dimethylation and decreased H3 acetylation during disease progression has been observed." (PMID 22414300, 2011). "Numerous studies using cell lines, knockout animals, and primary human cancer samples have demonstrated a crucial role for RUNX3 not only in normal development, but also in neoplasias, especially stomach cancers." (PMID 21867527, 2011). "The negative correlation between RUNX3 methylation and age suggests that the influence of RUNX3 methylation on gastric cancer is reduced in older individuals." (PMID 21867527, 2011). "However, the association between RUNX3 promoter methylation and gastric cancer remains unclear." (PMID 21867527, 2011). "Among the 17 retrieved articles, 16 observations in 15 studies used methylation-specific polymerase chain reaction to explore RUNX3 promoter methylation in gastric cancer tissues (n = 928) and normal tissues (n = 812), with a total sample size of 1740 cases." (PMID 21867527, 2011). "RUNX3 protein expression is decreased about 45-60% in human gastric cancer and has been detected in some human malignancies such as those of the colon, lung, pancreas, and bile duct." (PMID 21205319, 2011). "It has been reported that the over expression of Runx3 in gastric cancer cells down regulates Bcl-2 and directly activates the promoter activity of Bim to enhance TGF-β-dependent apoptosis, therefore, sensitizes cancer cells to chemotherapeutic drugs." (PMID 24250365, 2011). "The overall results demonstrated that RUNX3 methylation was more frequent in intestinal-type, compared with diffuse-type gastric carcinomas (OR = 2.62, 95%CI: 1.33, 5.14)." (PMID 21867527, 2011). "The TRAPPC2L, DUSP6, MLH1 and RUNX3 genes more than 3-kb distal from the nearest retroelements were similarly overmethylated in the H. pylori positive mucosa (43%) and gastric cancers (LOH-B, 44%; LOH-L, 47%; LOH-H, 33%)." (PMID 21092120, 2010). "RUNX3 is inactivated in more than 80% of human gastric cancer by CpG island hypermethylation, protein mislocalization and point mutations." (PMID 19521519, 2009). "In fact, RUNX3 is inactivated in more than 80% of human gastric cancer by gene silencing and protein mislocalization." (PMID 19521519, 2009). "RUNX3 has multiple functions and was at first reported to correlate with the genesis and progression of human gastric cancer as a tumor suppressor." (PMID 19521519, 2009). "In gastric cancer, RUNX3 activity is most commonly reduced through a mechanism involving RUNX3 promoter hypermethylation and subsequently decreased mRNA expression." (PMID 18551179, 2008). "Recently, it has been reported that RUNX3 was one of the tumour suppressor genes in gastric cancer and testicular yolk sac tumour." (PMID 18475302, 2008). "Hypermethylation and consequent silencing of p16, p57 and runX3 have been shown to occur at the early stages of gastric carcinoma." (PMID 19412438, 2007). "RUNX3 shows remarkable downregulation in gastric cancers compared to the surrounding mucosa, and the percentage of downregulation increases as the cancer stage progresses." (PMID 15685235, 2005). "In cases of remnant gastric cancer, the rate of downregulation of RUNX3 of adjacent mucosa was 39.2% in RB and 47.6% in RM, which are higher than that of GCI (19.5%)." (PMID 15685235, 2005). "It is likely that RUNX3 promotes a distinct metastasis program in gastric cancer." (PMID 38240752, 2024).
gastric cancer (continued). "However, miR-130a In gastric cancer, miR-130a has been reported to promote migration, invasion, and proliferation by targeting Runt-related transcription factor 3 (RUNX3)." (PMID 39263322, 2024). "Moreover, we noted RUNX3 expression in histopathologic vascular invasion and lymph node metastasis from stomach cancer." (PMID 38240752, 2024). "Additionally, in gastric cancer, RUNX3 plays a role in suppressing cell proliferation and tumor growth, an effect mediated through the co-activation of the transcription factor Ets-1 by JMJD1A and the reduction in H3K9me1/2 levels." (PMID 38430423, 2024). "This protein may ubiquitinate Runx3 (runt-related transcription factor 3) and increase the invasion of gastric cancer cells." (PMID 36507941, 2023). "RUNX3 has initially been reported as a tumour suppressor in gastric cancer." (PMID 37759525, 2023). "An interplay between CagA, Smurf1/2, and RUNX3 could suggest that CagA recruits Smurfs to ubiquitinate RUNX3 in gastric cancer." (PMID 36899853, 2023). "Therefore, the interaction between HOTAIR and Mex3b can induce the ubiquitination of Runx3 protein and enhance the invasion ability of gastric cancer cells, and providing a potential therapeutic target for gastric cancer metastasis." (PMID 35813070, 2022). "Increasing RUNX3 expression by demethylating its promoter could restrict the cell proliferation in gastric cancer." (PMID 36429115, 2022). "More molecular experimental and clinical research is needed to investigate whether high expression of RUNX3 has an essential role in gastric cancer." (PMID 35522574, 2022). "For example, while PD-1hi CD8+ Trm cells highly express cell adhesion and tissue positioning markers, including CD69 and integrins CD11c, CD49a, CD49b, and CD103 in HCC, CD103+CD8+ Trm cells express tissue residency-promoting molecules, such as CD69, CD49a, and RUNX3, in gastric cancer." (PMID 35096624, 2021). "Also, the RUNX3 signaling pathway regulating TIMP3 can be effective in MMP-9 activity in gastric cancer invasion." (PMID 34054953, 2021). "Consistently, IF analysis of human gastric tumor tissue sections showed that gastric cancers had low expression of RUNX3 compared to the normal, while gastric cancers had high expression of G9a compared to the normal, and this pattern was also seen in various human cancers." (PMID 33116296, 2021). "Furthermore, it was proposed that RUNX3 suppresses growth in gastric cancer cells by changing the partner of YAP from TEAD4 to RUNX3." (PMID 34831147, 2021). "RUNX3 has been described as a tumor suppressor gastric cancer and lung cancer." (PMID 33401247, 2020). "Thus, we consider this to be preliminary data showing the level of methylated RUNX3 circulating in the blood to be a promising biomarker of early gastric cancer." (PMID 32224873, 2020). "Indeed, the serum CORD assay of methylated RUNX3 resulted in a sensitivity of 50% for the detection of early gastric cancer, showing better performance compared to that in the previous reports (0–19.0%)." (PMID 32224873, 2020). "RUNX3 can be phosphorylated by a spectrum of oncogenic kinases, like Pin1, Src, Pak1, to translocate from nucleus to cytoplasm, thus leading to its subcellular mislocation in human breast, pancreatic and gastric cancer." (PMID 32307917, 2020). "Furthermore, miR-185 can be therapeutic target for gastric cancer because it can induce apoptosis via the activation of the Runx3 gene." (PMID 32872332, 2020). "This characteristic that contributes to tumorigenesis and progression has also been discovered in gastric cancer, which may be achieved by mediation of RUNX3 and Ras-related protein activator like 1 (RASAL1)." (PMID 31640738, 2019).
gastric cancer (continued). "RUNX3 was first suggested to be a tumour suppressor in gastric cancer." (PMID 31467531, 2019). "However, in gastric cancer, exogenous miR-532-5p was found to accelerate the cell growth via targeting RUNX3 and acting as an oncogenic miRNA27." (PMID 31570702, 2019). "RUNX3 is strongly implicated as tumor suppressor for gastric cancer and the absence of RUNX3 expression is proposed to be linked to gastric cancer because expression of RUNX3 is not observed in more than 45% of the gastric cancer patients." (PMID 30847297, 2019). "However, it promotes cell growth, migration and invasion in gastric cancer cells and melanoma by down-regulating RUNX3." (PMID 29324832, 2018). "This suggests that the expression of RUNX3 is correlated with the occurrence of gastric cancer, such that a reduced expression of RUNX3 may facilitate the development of gastric cancer." (PMID 28828318, 2017). "RUNX3 is correlated with the occurrence and development of advanced gastric cancer." (PMID 28828318, 2017). "Thus, current research supports the theory that the expression of RUNX3 protein is closely correlated with the occurrence of gastric cancer." (PMID 28828318, 2017). "The patients with advanced gastric cancer who had low expression of RUNX3 gene were treated with holistic nursing while routine nursing was taken for those patients who had normal or high expression of RUNX3 gene." (PMID 28828318, 2017). "The expression of RUNX3 is significantly reduced in gastric cancer." (PMID 27464701, 2016). "In gastric cancer, miR-106a targeting of RUNX3 is involved in multidrug resistance." (PMID 26375442, 2015). "One study showed that RUNX3 could interact with FOXO3a to induce the expression of pro-apoptotic proteins, thereby triggering apoptosis in gastric cancer cells." (PMID 25948105, 2015). "Therefore, miR-130a regulated gastric cancer cell migration, invasion and proliferation by targeting RUNX3." (PMID 26134263, 2015). "miR-130a and miR-495 downregulate RUNX3 protein expression in gastric cancer cells." (PMID 26375442, 2015). "In addition, some researcher supposed that HOXA13 was probable to regulate TGF-β signaling by interacting with RUNX3 (runt-related transcription factor 3) mediated by SMADs to promote tumor progression in gastric cancer." (PMID 26356815, 2015). "The result shows that miR-130a attenuates RUNX3 expression in gastric cancer tissues." (PMID 26134263, 2015). "It is worth noting that RUNX3 expression is kept at an extremely low level both in gastric cancer-derived cells and gastric cancer tissues, which might be due to the hypermethylation of the CpG island of RUNX3 exon 1 region." (PMID 26512706, 2015). "However, the majority of data have been from the analysis of commonly methylated genes in the serum of patients with gastric cancer such as RUNX3 and p16 which were shown to be helpful for detection of gastric cancer." (PMID 26550574, 2015). "miR-130a expression was inversely correlated with that of RUNX3 in gastric cancer tissues." (PMID 26134263, 2015). "For example, RUNX3 in cooperation with FOXO up-regulates Bim in gastric cancer cells." (PMID 25909227, 2015). "Additionally, miR-130a was identified as an oncogene that promotes gastric cancer tumorigenesis by targeting RUNX3." (PMID 26134263, 2015). "In vivo, RUNX3 inhibits human gastric cancer cells metastasis." (PMID 24447545, 2014). "Effective therapy targeting the RUNX3 pathway may help control gastric cancer cell invasion and metastasis by inhibiting the EMT." (PMID 24447545, 2014). "Gastric cancer cells transfected with RUNX3 siRNA showed decreased RUNX3 protein expression." (PMID 24447545, 2014). "Therefore, we investigated the expression of the epithelial and mesenchymal markers E-cadherin and vimentin, respectively, in gastric cancer cells transfected with control siRNA and RUNX3 siRNA." (PMID 24447545, 2014). "Targeting the RUNX3 pathway may help to control gastric cancer invasion and metastasis by inhibiting the EMT." (PMID 24447545, 2014).
gastric cancer (continued). "We then examined whether RUNX3 overexpression inhibited the metastasis of gastric cancer cells in vivo." (PMID 24447545, 2014). "Therefore, RUNX3 downregulated vimentin and inhibited gastric cancer cell invasion through an miR-30a–dependent mechanism." (PMID 24447545, 2014). "Finally, we determined RUNX3 and vimentin expression in 55 primary tumour samples from gastric cancer patients by western blot analysis and miR-30a expression by qRT-PCR analysis." (PMID 24447545, 2014). "Besides gastric cancer, it has been reported that ectopic expression of RUNX3 was observed in various cancers including breast cancer, glioma." (PMID 24475196, 2014). "Runx3 is reported as a tumor suppressor gene for gastric cancer, and may be important in the development of hepatocellular carcinoma." (PMID 23874686, 2013). "Besides gastric cancer, it has been reported that reduced expression of RUNX3 was observed in various kinds of cancers, including breast cancer, colorectal cancer, glioma and melanoma." (PMID 23457532, 2013). "RUNX3 is frequently inactivated in gastric cancer by protein mislocalization." (PMID 24216700, 2013). "Indeed, it has been shown that RUNX3 is frequently detectable in cytoplasm of various human cancers including gastric cancer, colorectal cancer, and breast cancer." (PMID 24078903, 2013). "In gastric cancer cell lines, RUNX3-induced apoptosis depends on Bim expression." (PMID 21205319, 2011). "Runt-related transcription factor 3 (RUNX3) is known as a tumor suppressor gene for gastric cancer and other cancers, this gene may be involved in the development of hepatocellular carcinoma (HCC)." (PMID 21205319, 2011). "RUNX3/AML2/CBFA3/PEBP2αC expression is necessary for development of neuronal networks and the gastrointestinal tract, and its inactivation is strongly associated with gastric cancer." (PMID 21197465, 2011). "The role of the RUNX3 gene in gastric cancer is controversial." (PMID 21867527, 2011). "The pooled OR for RUNX3 methylation in cancer tissues compared with normal tissues was 5.63 (95%CI 3.15-10.06, z = 5.82, P < 0.0001), indicating an increased likelihood of methylation in gastric cancer tissue, compared with normal tissue." (PMID 21867527, 2011). "RUNX3 has been described as a gastric cancer tumor suppressor." (PMID 21205319, 2011). "This study performed on gastric cancer cell lines revealed that following treatment with the histone deacetylase inhibitor trichostatin A and the cytosine-methylation inhibitor 5-aza-2-deoxycytidine, down-regulation of RUNX3 was reversed." (PMID 22414300, 2011). "We systematically reviewed studies of RUNX3 promoter methylation and gastric cancer published in English or Chinese from January 2000 to January 2011, and quantified the association between RUNX3 promoter methylation and gastric cancer using meta-analysis methods." (PMID 21867527, 2011). "RUNX3 has been reported to induce apoptosis in a gastric cancer cell study." (PMID 21205319, 2011). "Levanon and colleagues questioned the causal relationship between loss of RUNX3 expression and gastric cancer, and reported that RUNX3-deficient mice did not develop gastric hyperplasia or gastric tumors." (PMID 21867527, 2011). "However, the role of RUNX3 in the regulation of gastric epithelial cell growth and its tumor suppressor activity in gastric cancer remain to be clarified." (PMID 21867527, 2011). "Besides gastric cancer, it has been reported that reduced expression of RUNX3 was observed in various cancers including bladder, liver, colorectal and lung cancers." (PMID 19521519, 2009). "In addition, loss of function of RUNX3 caused by DNA hypermethylation, LOH at gene locus, and mutation correlated with the progression of primary gastric cancers." (PMID 18475302, 2008). "RunX3 methylation has been detected in many premalignant lesions of gastric carcinomas, including 8.1% of chronic gastritis, 28.1% of intestinal metaplasia, 27.3% of gastric adenomas and 64% gastric carcinomas." (PMID 19412438, 2007).